NF2 (NF2, moesin-ezrin-radixin like (MERLIN) tumor suppressor)
Diseases named in the same sentence as NF2 in open-access papers (continued):
Sharing a sentence is not in itself a finding about the gene and the disease.
Vestibular schwannoma (continued). "Protein tyrosine nitration was found in samples from three vestibular schwannomas from NF2 patients." (PMID 31171721, 2019). "NF2 is a central disorder, with tumours occurring in cranial and spinal nerves, most commonly bilateral vestibular schwannomas." (PMID 30382390, 2018). "Although the presence of vestibular schwannomas (VS) in NF2 has previously been considered a distinguishing feature, it is now recognized that LZTR1 schwannomatosis can be associated with VS." (PMID 30382390, 2018). "The great majority of sporadic vestibular schwannomas (VSs) are due to the inactivation of the NF2 gene." (PMID 28710469, 2017). "Both patients with NF2 (DD, LL) showed bilateral vestibular schwannoma with one ear showing larger tumour than the other." (PMID 27174775, 2017). "We found that SFN had inhibitory effects on primary human vestibular schwannoma cells and a human NF2-derived VS cell line in vitro, as well as on an in vivo allograft model of VS." (PMID 27805058, 2016). "Clinical analysis has shown that vestibular schwannomas overexpress ErbB2/3 and that EGFR and its ligand are up-regulated in the majority of NF2-related vestibular schwannomas." (PMID 24393766, 2014). "There have also been several patients with neurofibromatosis type 2 (NF2) reported in the literature who have ring chromosome 22 with NF2 features such as multiple intracranial meningiomas or vestibular schwannomas." (PMID 25784960, 2014). "Vestibular schwannomas are benign tumors that arise from Schwann cells in the VIII cranial pair and usually present NF2 gene mutations and/or loss of heterozygosity on chromosome 22q." (PMID 23776562, 2013). "Mutations in the neurofibromatosis type 2 (NF2) tumor-suppressor gene have been identified in not only NF2-related tumors but also sporadic vestibular schwannomas (VS)." (PMID 22295085, 2012). "NF2 is an autosomal dominant disease characterized by development of bilateral vestibular schwannomas and other benign tumors in central nervous system." (PMID 21072183, 2010). "MLPA and LOH analysis with two NF2 linked microsatellite markers (D22S268 and NF2CA3) showed loss of one copy of the NF2 gene in the vestibular schwannoma." (PMID 19772601, 2009). "For instance, in a study conducted by Meng and colleagues, they discovered that Merlin (NF2) could induce the formation of phase-separated droplets when examining tissue samples extracted from individuals with vestibular schwannoma." (PMID 40104511, 2025). "This is because unilateral vestibular schwannomas may occur in patients with mosaic NF2-related SWN but also in patients with germline LZTR1 PVs." (PMID 40794298, 2025). "Determining the volume of vestibular schwannomas, especially in cases with adjacent collision tumors, can take 20 to 30 min on average, leading to a total analysis time of nearly one hour for complex NF2 cases with large tumors." (PMID 39824854, 2025). "Similarly, NF2 exhibits significant clinical variability, with manifestations ranging from isolated vestibular schwannomas to extensive intracranial and spinal tumours leading to severe neurological deficits." (PMID 40843672, 2025). "Unlike sporadic cases, NF2-associated vestibular schwannomas (VSs) often occur bilaterally and at a younger age, typically in adolescence or early adulthood, due to the genetic predisposition for tumor development." (PMID 39685944, 2024). "It is noteworthy that the M1 marker iNOS exhibited a notably low expression level in both sporadic and NF2-associated vestibular schwannoma (VS), regardless of the tumor growth rate." (PMID 38817895, 2024). "Univariate logistic regression analysis revealed that, of the five microvascular parameters derived using the new method, ve estimates (AUC = 0.896, p = 0.02) showed the greatest ability in the prediction of 90-day response in NF2-related vestibular schwannoma." (PMID 37765090, 2023). "NF2 is characterized by development of bilateral vestibular schwannomas." (PMID 37087513, 2023).
Vestibular schwannoma (continued). "However, several previous reports have suggested that promoter methylation is an uncommon mechanism of NF2 inactivation in sporadic vestibular schwannomas." (PMID 35626200, 2022). "The “two-hit” model of the NF2 genes can explain many of the sporadic vestibular schwannoma cases." (PMID 35626200, 2022). "However clinical lines are blurred between NF2 and schwannomatosis, as unilateral vestibular schwannomas have been reported in both conditions, as have other features like meningiomas." (PMID 35698239, 2022). "Thus, the effect of epigenetic modification of the NF2 gene on the pathogenesis of sporadic vestibular schwannomas is controversial." (PMID 35626200, 2022). "Conventional chemotherapy has not been demonstrated to be effective for NF2-associated vestibular schwannomas, and therefore many trials have focused on inhibition of potential NF2-associated molecular pathways." (PMID 34885143, 2021). "Unlike NF2-associated vestibular schwannomas, bevacizumab has been demonstrated to have limited benefit, with only a subset of patients demonstrating radiographic response which appears to be of limited duration." (PMID 34885143, 2021). "NF2-related vestibular schwannomas in the recurrent setting are often treated with Bevacizumab." (PMID 33445724, 2021). "The presenting symptoms of the tumor suppressor gene syndrome neurofibromatosis type 2 (NF2) are often non-specific and unrelated to the disease hallmark bilateral vestibular schwannomas (VS)." (PMID 32825434, 2020). "Because we observed an increase in tyrosine nitration in vestibular schwannomas from NF2 patients and in human and mouse MD-Schwann cells, we investigated whether Hsp90 was endogenously nitrated in these cells and in tumor samples." (PMID 31171721, 2019). "Peroxynitrite production was investigated in vestibular schwannomas (VS) from NF2 patients, human and mouse wildtype (WT) Schwann cells, as well as in human and mouse Schwann cells deficient in merlin expression either by merlin knockdown, or by merlin knockout as a result of NF2 exon 2 deletion." (PMID 31171721, 2019). "CXCR4 expression was not significantly different in NF2-associated vestibular schwannomas than in sporadic vestibular schwannoma." (PMID 29515781, 2018). "Furthermore, the histology and growth pattern of vestibular schwannomas (VS) in NF2 are different from that of sporadic VS." (PMID 27921248, 2017). "The hypothesis has been strongly demonstrated in the NF2 gene in NF2-related VSs, the familial forms of vestibular schwannomas." (PMID 28710469, 2017). "Having established that iRGD-targeted delivery of siRNA can lead to receptor- and sequence-specific suppression of TNFα gene expression in an NF2-derived vestibular schwannoma cell line, we then evaluated the ability of iRGD nanoparticles to mediate RNAi in primary human VS cultures." (PMID 29018206, 2017). "The clinical overlap between schwannomatosis and NF2 renders differential diagnosis somewhat difficult, particularly in sporadic and mosaic cases with multiple schwannomas but without bilateral vestibular schwannomas and detectable germline NF2 gene mutations." (PMID 27921248, 2017). "In addition, analysis of NF2-null vestibular schwannomas demonstrated dysregulation of MET expression and other associated genes." (PMID 27363027, 2016). "Although NF2 is predominantly characterized by bilateral vestibular schwannomas, affected individuals may suffer from meningeomas, ependymomas, peripheral neuropathy and lesions affecting skin and eyes." (PMID 27467574, 2016). "Although no appropriate systematic studies are currently available, clinical observations suggest that recovery from facial nerve palsy is markedly reduced in NF2 patients when compared to individuals with sporadically occurring vestibular schwannomas (personal communication, Steffen Rosahl)." (PMID 27467574, 2016).
Vestibular schwannoma (continued). "Furthermore, epigenetic changes involving the NF2 gene and other tumor-related genes have also been investigated in vestibular schwannomas." (PMID 23354516, 2013). "The young age at which PRS-NF2 was diagnosed with bilateral vestibular schwannomas (15 years), the high tumor burden that included multiple spinal tumors, and the progressive nature of some of these tumors qualify her as having a severe form of NF2." (PMID 22436304, 2012). "Patients with NF2 are characterized by having bilateral vestibular schwannomas." (PMID 22567403, 2012). "Indeed, the literature prior to 1985 has many NF2 cases being described as part of von Recklinghausen disease, with bilateral vestibular schwannomas (VS) being included in a major patient series." (PMID 19545378, 2009). "However, in a certain percentage of sporadic vestibular schwannoma cases, no mutations in the NF2 gene or mutations in only one allele were detected." (PMID 35626200, 2022). "Additionally, the combination of NF2 gene mutations and loss of heterozygosity (LOH) caused by partial or complete loss of chromosome 22, where the NF2 gene is located, can lead to sporadic vestibular schwannoma." (PMID 35626200, 2022). "Future studies might consider investigating the ability to visualize the internal acoustic canal, cerebellopontine angle, or other features of the inner ear from an MRI scan of a HI recipient—this would be particularly interesting when following individuals with vestibular schwannomas or NF2." (PMID 33788034, 2021). "Indeed, MEK 1 and 2 inhibitors are being studied for NF2-related vestibular schwannomas." (PMID 33445724, 2021). "Previous research has shown that although NF2 gene mutation is the major cause of vestibular schwannoma (VS), it may not directly participate in cystic VS (CVS)." (PMID 30953268, 2019). "In addition to the pathognomonic development of bilateral vestibular schwannomas, patients with NF2 are prone to the development of other benign tumors of the central and peripheral nervous system, including intracranial and spinal meningiomas, ependymoma, and central and peripheral schwannomas." (PMID 30356733, 2018). "Furthermore, bilateral vestibular schwannomas, the hallmark feature of NF2, have not been reported in patients with schwannomatosis." (PMID 27921248, 2017). "However, these mice do not develop vestibular Schwannomas, the hallmark tumors of human NF-2." (PMID 39415595, 2024). "As previous studies implicated signaling downstream of MET as a potential therapeutic target in vestibular schwannoma, we assessed the consequences of inhibiting MET in NF2-null Schwann cells." (PMID 27363027, 2016). "Lapatinib, which targets EGFR and ErbB-2, is being examined in both a phase 0 study treating vestibular schwannomas (NCT00863122) and a phase II (NCT00973739) trial for its effectiveness in all NF2 related tumor types." (PMID 24393766, 2014). "No fewer than 43% of the patients with at least one non-vestibular schwannoma, and who did not meet the clinical criteria for NF2-related SWN, exhibited somatic mosaicism for an NF2 PV and hence had mosaic NF2-related SWN." (PMID 40794298, 2025). "The absence of the bilateral vestibular Schwannoma in both patients argued against the diagnosis of NF2." (PMID 39857711, 2025). "It should be noted that somatic mosaicism is quite frequent in NF2-related SWN cases, being observed in at least 33% of de novo patients with bilateral vestibular schwannomas and in up to 60% of de novo patients with unilateral vestibular schwannomas." (PMID 40794298, 2025). "The diagnosis of Schwannomatosis is based on the presence of multiple schwannomas without vestibular schwannomas and the lack of a clear family history of NF2." (PMID 40764996, 2025). "Moreover, mutations in NF2 moesin-ezrin-radixin-like (MERLIN) tumor suppressor (NF2/merlin) indirectly disrupt signaling pathways such as RAS, contributing to the formation of tumors like bilateral vestibular schwannomas." (PMID 41359105, 2025).
Vestibular schwannoma (continued). "The present study found that the majority of NF2 patients was treated with proton radiotherapy as salvage treatment for vestibular schwannoma and did not require additional interventions." (PMID 36975476, 2023). "Unilateral vestibular schwannoma develops sporadically in non-NF2-related schwannomatosis patients for which there are no drug treatment options available." (PMID 37680691, 2023). "The overlap from both the vestibular schwannomas occurring in LZTR1-related schwannomatosis and mosaic NF2 mimicking schwannomatosis has necessitated a re-evaluation of the existing diagnostic criteria and an international effort has defined new criteria that will be published in 2022." (PMID 35361920, 2022). "Schwannomatosis was only recognized as a clinically separate entity from NF2 in the late 1990s, upon identifying a subset of patients with multiple non-intradermal schwannomas but no vestibular schwannomas." (PMID 35698239, 2022). "Clinically, schwannomatosis is distinguished from NF2 by the absence of bilateral vestibular schwannomas and ependymomas." (PMID 35361920, 2022). "In contrast, our model for malignant transformation in vestibular schwannoma suggests that the last alterations before malignancy should be in an unidentified tumour suppressor (or suppressors) TSX, with NF2 already being inactivated or lost in the benign tumour." (PMID 36097176, 2022). "Lapatinib showed objective activity in 4 out of 17 patients with NF2-related progressive vestibular schwannoma in a phase II trial, whereas erlotinib was not effective in a retrospective series with 11 NF2 patients." (PMID 34072574, 2021). "This group usually comes into medical attention with features not related to vestibular schwannoma (VS) but which are rather non-specific and this most often not right away recognized as feature pointing to NF2 in the differential diagnosis." (PMID 32537663, 2020). "Expanded criteria, aimed at identifying additional patients that do not have a family history of NF2 or vestibular schwannomas, were proposed in later classification systems (National Neurofibromatosis Foundation and Baser (1997))." (PMID 31161239, 2020). "Schwannomatosis is characterized by the development of multiple schwannomas in the absence of other NF2-defining lesions such as bilateral vestibular schwannomas or ependymomas." (PMID 31652973, 2019). "We examined CXCR4 expression in vestibular schwannomas (VS) from patients with and without neurofibromatosis type 2 (NF2) and correlated the levels with the patients’ clinical characteristics." (PMID 29515781, 2018). "Further, somatic mosaicism in NF2 is not rare, since it is detected in 33% of sporadic NF2 cases with bilateral vestibular schwannomas and in up to 60% of patients with unilateral vestibular schwannoma." (PMID 27921248, 2017). "The second describes a patient with a unilateral vestibular schwannoma that developed contralateral cranial MPNST as such neither report refers to a patient with proven NF2." (PMID 23036231, 2012). "Given the high incidence of CNS tumours (mostly vestibular schwannomas) in NF2 patients, it is not possible to extrapolate the data in this study to our work." (PMID 16786042, 2006). "However, other studies on celecoxib, aspirin, and COX-2 inhibitors in non-steroidal anti-inflammatory drugs (NSAIDs) demonstrated that no growth inhibitory effect was shown for celecoxib on NF2 or aspirin on the patients with vestibular schwannoma." (PMID 37629179, 2023). "Therefore, the GG recommended that unilateral vestibular schwannomas should not be considered an exclusion criterion for the diagnosis of schwannomatosis in the absence of proven germline or mosaic NF2." (PMID 35361920, 2022). "Patients with NF2 have been demonstrated to have numerous tumor nodules along the nerve, indicating that vestibular schwannomas in this population are likely composed of multiple tumor nodules instead of one discrete tumor, thereby complicating surgical resection." (PMID 34885143, 2021).
Vestibular schwannoma (continued). "A larger study on SMARCB1 and NF2 mutation-negative patients revealed LZTR1 mutations in 6 of 16 patients with familial SWN (38%), 11 of 49 sporadic patients (22%), and 2 of 39 patients with unilateral vestibular schwannoma." (PMID 34072574, 2021). "However, there are no data on CXCR4 expression in vestibular schwannomas in patients with or without NF2, nor has CXCR4 expression been correlated with other clinical data." (PMID 29515781, 2018). "The present investigation demonstrates for the first time in a larger cohort that CXCR4 is overexpressed in pure vestibular schwannomas with and without NF2 and could therefore play a role in the pathogenesis of these tumors." (PMID 29515781, 2018). "However, the term schwannomatosis or neurilemmomatosis has been used to describe patients with multiple non-vestibular schwannomas with no other stigmatas of NF-2 or NF-1." (PMID 19574706, 2009). "Despite the clinical overlap between non-NF2-related SWN and NF2-related SWN, it became clear quite early on that they are distinct clinical and genetic entities since patients with non-NF2-related SWN do not exhibit bilateral vestibular schwannomas, which is a hallmark feature of NF2-related SWN." (PMID 40794298, 2025). "Finally, MTVSs had a higher rate of NF syndrome (commonly NF2) compared with spinal MPNSTs (commonly NF1) (18.5% vs. 14.0%), and NF2 patients with a malignant transformation of a vestibular schwannoma may have a poorer prognosis compared to NF1 patients with spinal MPNST." (PMID 33937063, 2021).